CRLF3 (cytokine receptor like factor 3)
Description:
May play a role in the negative regulation of cell cycle progression.
Synonyms: CREME-9; CREME9; CRLM9; CYTOR4; FRWS; p48.2
Tractability: Antibody: its Gene Ontology location is reachable by antibodies, with high confidence. PROTAC: ubiquitination databases record sites on it; its protein half-life has been measured.
Gene: Protein-coding gene on chromosome 17 (30,769,388 to 30,824,692, reverse strand). Ensembl gene ENSG00000176390.
Subcellular location: Cytoplasm
Subcellular location (Human Protein Atlas): Cytosol; Plasma membrane
Gene Ontology:
Molecular function: identical protein binding; protein binding; DNA binding
Biological process: negative regulation of cell growth; negative regulation of G1/S transition of mitotic cell cycle; positive regulation of DNA-templated transcription; positive regulation of receptor signaling pathway via JAK-STAT; positive regulation of transcription by RNA polymerase II
Cellular component: cytoplasm; cytosol; nucleus
Genetic constraint (gnomAD): Loss-of-function variants: 28 observed, 44.07 expected, observed/expected ratio (o/e) 0.64, 90% interval 0.47 to 0.87. The upper end of that interval is the gene's LOEUF score, 0.87, which puts it in group 3 of 6, group 1 being the genes least tolerant of losing a copy. Missense variants: 425 observed, 467 expected, observed/expected ratio (o/e) 0.91, 90% interval 0.84 to 0.99. Synonymous variants: 210 observed, 178.44 expected, observed/expected ratio (o/e) 1.18, 90% interval 1.05 to 1.32.
Homologues: Orthologues: chimpanzee CRLF3 (100% identical), macaque CRLF3 (99% identical), dog CRLF3 (95% identical), rabbit CRLF3 (95% identical), pig CRLF3 (94% identical), mouse Crlf3 (93% identical), rat Crlf3 (86% identical), guinea pig CRLF3 (86% identical), tropical clawed frog crlf3 (69% identical), zebrafish crlf3 (67% identical), Drosophila melanogaster elg1 (10% identical). Paralogues in human: ATAD5 (20% identical).
Diseases named in the same sentence as CRLF3 in open-access papers:
CRLF3 is named in the same sentence as 31 diseases in open-access papers, as found by Europe PMC text mining. Sharing a sentence is not in itself a finding about the gene and the disease. The quoted sentences say what the papers report.
autism (5 papers, 2021 to 2024). Persistent deficits in social interaction and communication and interaction as well as a markedly restricted repertoire of activity and interest as well as repetitive patterns of behavior. "Other studies have suggested roles in neuronal differentiation and function, with a CRLF3 variant associated with the extent of autism in NF1 patients." (PMID 35795682, 2022). "A specific role in the development of the NF1 microdeletion-associated phenotype and in particular autism has recently been demonstrated for the cytokine receptor-like factor 3 (CRLF3) gene located within the NF1 microdeletion region." (PMID 34681033, 2021). "CRLF3 has been associated with a variety of diseases including neurofibromatosis type I, cutaneous Leishmaniasis, cutaneous squamous cell carcinoma, amyotrophic lateral sclerosis, autism and cancer." (PMID 37168680, 2023). "A single deleterious CRLF3 missense mutation (c.1166T > C, p.Leu389Pro) was recurrently identified in NF1 children with higher SRS-2 scores for autism evaluation." (PMID 38448973, 2024). "Taken together, these findings suggest an essential role for CRLF3 in both human brain development and autism." (PMID 34681033, 2021). "Taken together, these findings indicate an essential role for CRLF3 in both human brain development and autism." (PMID 34535841, 2021).
neurofibromatosis type 1 (4 papers, 2022 to 2026). A clinically heterogeneous, neurocutaneous genetic disorder characterized by cafe-au-lait spots, iris Lisch nodules, axillary and inguinal freckling, and multiple neurofibromas. "Cytokine Receptor Like Factor 3 (CRLF3) is a poorly studied but widely expressed 488 amino acid protein encoded in chromosome 17q11.2 in a region that is deleted in Neurofibromatosis type 1." (PMID 35051265, 2022). "The human CRLF3 gene was first identified (as cytokine receptor-related molecule 4 or CYTOR4) in the context of neurofibromatosis type 1 (NF1), a disease characterized by benign nerve tumors called neurofibromas in concert with melanocyte and skeletal defects, as well as cancer susceptibility." (PMID 40331935, 2025).
acute myeloid leukemia (3 papers, 2020 to 2025). Acute myeloid leukemia (AML) is a group of neoplasms arising from precursor cells committed to the myeloid cell-line differentiation. "Increased CRLF3 expression has also been observed in leukemia and lymphoma, while a rare UTP6–CRLF3 fusion has additionally been identified in acute myeloid leukemia, although its role in oncogenesis remains unclear." (PMID 40331935, 2025). "This is consistent with the upregulation of CRLF3 observed during the early cancerous stage of actinic keratosis, cutaneous squamous cell carcinoma and non-melanoma skin cancer, and its involvement in the UTP6-CRLF3 fusion in acute myeloid leukemia." (PMID 35795682, 2022).
cutaneous leishmaniasis (3 papers, 2021 to 2023). Leishmaniasis affecting the skin. "Human CRLF3 variants have been associated with lymphocyte percentage in the blood and risk of cutaneous leishmaniasis, while variants in the corresponding chicken gene are associated with an altered antibody response." (PMID 35795682, 2022).
Thrombocytopenia (3 papers, 2022 to 2026). A reduction in the number of circulating thrombocytes. "CRLF3 deficiency in mice leads to a sustained thrombocytopenia (25–48%)." (PMID 41602576, 2026). "To assess whether the thrombocytopenia in Crlf3-/- animals was driven by factors intrinsic to the haematopoietic compartment, we performed bone marrow (BM) transplants (BMT)." (PMID 35051265, 2022).
actinic keratosis (2 papers, 2021 to 2022). A precancerous lesion of the skin composed of atypical keratinocytes. "In contrast, the cytokine receptor-like factor 3 CRLF3 is expressed in normal skin, and shows pathologically enhanced expression in premalignant actinic keratosis and malignant squamous cell carcinoma." (PMID 32830257, 2021).
thrombocythaemia (2 papers, 2022 to 2023). "We thereby postulate that targeting CRLF3 has therapeutic potential for treatment of thrombocythaemia." (PMID 35051265, 2022). "It is less clear, however, whether these changes are coordinated with thrombocytosis, as some factors such as cytokine receptor-like factor 3 (CRLF3) regulate platelet formation in the hematopoietic bone marrow compartment without affecting leucocyte lineages." (PMID 36814334, 2023).
breast carcinoma (1 paper, 2025). "CRLF3 protein and antibodies were collectively increased in breast cancer (principally invasive carcinoma), with CRLF3 antibodies significantly elevated in early-stage breast cancer compared to controls, in HER2+ versus luminal A forms, and in both of these versus triple-negative (TN) forms." (PMID 40331935, 2025).
chronic obstructive pulmonary disease (1 paper, 2025). A chronic and progressive lung disorder characterized by the loss of elasticity of the bronchial tree and the air sacs, destruction of the air sacs wall, thickening of the bronchial wall, and mucous accumulation in the bronchial tree. "Thus, CRLF3 expression has been identified as a potential biomarker in chronic obstructive pulmonary disease (COPD), a disorder associated with enhanced type 1 and 3 immune responses." (PMID 40331935, 2025).
Essential Thrombocythaemia (1 paper, 2022). "Using a mouse model of JAK2V617F Essential Thrombocythaemia (ET), we show that a lack of CRLF3 leads to a long-term lineage-specific normalisation of the platelet count." (PMID 35051265, 2022).
neuroblastoma (1 paper, 2007). Neuroblastoma (NB) is the most common solid, extracranial childhood tumor. "Cluster 3 (Crlf3 and Mier 1) and Cluster 4 (Atp5c1, Suv39h1, Immt, Slca6) are not over-expressed in neuroblastoma cells lines and seem unlikely to play a role in neuroblastoma." (PMID 17397536, 2007).
skin cancer (1 paper, 2009). "Noticeably among the cytokine receptor-like factor 1 and 3 (Crlf1, Crlf3) that belong to the same family, Crlf3 has been found to be up-regulated in skin cancer." (PMID 19799787, 2009).
viral infection (1 paper, 2024). "In their experiments, Crlf3 interacted with TANK-binding kinase 1 (TBK1) and promoted its degradation via ubiquitination, presumably preventing cell response to viral infection." (PMID 38448973, 2024).
tumor (7 papers, 2017 to 2025). "Expression and functional studies have increasingly indicated roles for CRLF3 in neuronal and hematopoietic cells, with its perturbation linked to neurological disorders, immune disruption and various neoplasms." (PMID 40331935, 2025). "CRLF3 has been further implicated in various other diseases, notably including neoplasia, especially carcinomas." (PMID 40331935, 2025). "In addition, freshly isolated tumor tissues and some tumor cell lines show elevated CRLF3 expression." (PMID 31680856, 2019). "Additionally, some tumor cell lines and freshly isolated tumor tissues contain elevated levels of CRLF3 Human CRLF3 includes 442 amino acids and contains a number of characteristic predicted domains." (PMID 29393890, 2018). "Moreover, we show that EV-3/CRLF3 signaling mediates protection of human cells indicating that CRLF3 can be selectively targeted by Epo-like ligands to counteract neurodegenerative diseases without simultaneously promoting inappropriate erythropoiesis and tumor growth." (PMID 37168680, 2023).
cancer (5 papers, 2020 to 2025). A tumor composed of atypical neoplastic, often pleomorphic cells that invade other tissues. "Disruption of CRLF3 has been associated with neurological disorders, while its overexpression has been observed in a range of cancers." (PMID 40331935, 2025). "However, the impacts of CRLF3 are not universal, since some cancer types are associated with reduced expression or mutations that are predicted to be loss-of-function." (PMID 40331935, 2025).
CRLF3 also shares sentences with these, for which no sentence is quoted: amyotrophic lateral sclerosis (3 papers); cutaneous squamous cell carcinoma (2); autism spectrum disorder (1); developmental delay (1); intellectual disabilities (1); invasive carcinoma (1); leishmaniasis (1); leukemia (1); lymphoma (1); malignant squamous cell carcinoma (1); neurodegenerative disease (1); neurofibroma (1); neurological disorders (1); non-melanoma skin carcinoma (1); Thrombocytosis (1); unipolar depression (1).